ITGAV (integrin subunit alpha V)
Diseases named in the same sentence as ITGAV in open-access papers (continued):
Sharing a sentence is not in itself a finding about the gene and the disease.
prostate carcinoma (21 papers, 2013 to 2025). A carcinoma that arises from epithelial cells of the prostate gland. "In prostate cancer cells with metastatic initiation ability, the expression of ITGAV functionally participates in the acquisition and maintenance of prostate cancer stemness." (PMID 39239559, 2024). "In short, our study found that miR-197 affected the development of prostate cancer by regulating ITGAV." (PMID 34195187, 2021). "Oncogenic molecules transferred by large oncosomes include integrin alpha V (ITGAV) which promotes prostate cancer aggressiveness such as adhesion and invasion via AKT activation, and microRNA-1227 which boosts the migration of cancer-associated fibroblasts." (PMID 33003285, 2020). "In this study, we showed that ITGAV, the member of the integrin receptor family, is present as a “soluble” protein in the CM produced by prostate cancer cells and can be found in first pass urine collected without preceding prostate massage." (PMID 33791193, 2020). "Interestingly, in TCGA database, the expression of TβRI and THBS1, as well as TβRI and ITGAV in prostate cancer shows the correlations." (PMID 39304722, 2024). "The interaction of ECM proteins with the TβRI in the migratory prostate cancer cells in response to TGFβ1 was demonstrated by several different techniques to reveal that THBS1 mediates cell migration by interacting with integrin subunit alpha V (ITGAV) and TβRI." (PMID 39304722, 2024). "Then, we verified that miR-197 expression affects the proliferation, invasion, and metastasis of prostate cancer cells by regulating integrin subunit alpha V (ITGAV) expression through STAT5 pathway, and the results indicated that the miR-197 inhibitor can be a prostate cancer suppressor." (PMID 34195187, 2021). "Integrin receptor antagonists, in the form of RGD-antagonists or antibodies, have been shown to decrease angiogenesis, tumor growth and metastasis in several solid tumor types in which ITGAV is upregulated, including breast cancer, melanoma and prostate cancer." (PMID 25247809, 2014). "Although some integrin subtypes have been shown to be associated with perineural invasion in prostate cancer and carcinomas of the head and neck, no previous study has demonstrated a relationship between over-expression of ITGAV and the presence of perineural invasion in CRC." (PMID 23705994, 2013). "In prostate cancer, for example, AKT activation has been described as an additional mechanism for ITGAV involvement in a recent study." (PMID 34174926, 2021). "The HOXB13/HOXA11-AS axis also regulated integrin subunits (ITGAV and ITGB1) specific to prostate cancer bone metastasis." (PMID 33514011, 2021). "Additionally, researchers have found that the expression of ITGAV and ITGA6 is higher in ALDHhigh prostate cancer cells compared to ALDHlow cells." (PMID 39239559, 2024). "We compared the expression levels of eight integrin subunits (ITGA2, ITGA5, ITGAV, ITGB1, ITGB3, ITGB4, ITGB5, and ITGB6), HOXB13, HOXA11-AS, CCL2, CXCL12, and IBSP in prostate cancer tissues that had metastasized to bone, lymph nodes, lungs, liver, and other organs." (PMID 33514011, 2021). "In short, our study verified that miR-197 regulates the development of PCSCs through STAT5 pathway by targeting ITGAV, and the AbCD133@MSNs@GNR@miR-197 inhibitor could be a potential suppressor used in prostate cancer treatment." (PMID 34195187, 2021).
colorectal cancer (19 papers, 2015 to 2025). A primary or metastatic malignant neoplasm that affects the colon or rectum. "In particular, the integrin subunit αv gene ITGAV is overexpressed and associated with progression and spread of colorectal cancer." (PMID 32847144, 2020). "While overexpression of ITGAV was linked to progression and perineural invasion in colorectal cancer, ITGB1 expression in tumors was associated with shortened overall survival and shortened disease-free survival in a large cohort of patients with colorectal tumor." (PMID 30473751, 2018). "Existing studies have shown that ITGAV overexpression is related to the progression of some tumors, such as glioblastoma and laryngeal, breast, esophageal, and colorectal cancers." (PMID 36345604, 2023). "In other diseases such as liver cancer, ITGAV has been shown to be involved in the occurrence and development of breast, nasopharyngeal, liver and colorectal cancers." (PMID 36388191, 2022). "In lung and colorectal cancers, ITGAV knockdown reduced cancer stem cell sphere generation efficiency and cell migration." (PMID 31402560, 2019). "For instance, ITGA11 is overexpressed in colon cancer samples when compared to normal adjacent tissue, while abnormal levels of ITGAV and ITGB6 in colorectal cancer has been associated with epithelial to mesenchymal transition, cancer progression, invasiveness, metastasis and a worse prognosis." (PMID 39167197, 2024). "Additionally, related researches showed the over-expression of ITGAV was closely related to the development of colorectal cancer and spreading of colorectal cancer cells via perineural invasion." (PMID 33441929, 2021). "Many of the other differentially expressed proteins have been described in colorectal cancer progression, including integrins of which ITGA11, ITGAV (also among the top 10 hub proteins) and ITGB6 were altered in this study." (PMID 39167197, 2024). "For example, it was uncovered that the apoptosis-inducing potential of miR-217-5p can induced apoptosis via blocking multiple target genes PRKCI, BAG3, ITGAV and MAPK1 in colorectal cancer cells." (PMID 36352482, 2022). "MiR-217-5p could induce apoptosis in colorectal cancer cells by regulating multiple target genes, including PRKCI, BAG3, ITGAV, and MAPK1 in the ERK-MAPK signaling pathway." (PMID 35737029, 2022).
glioma (18 papers, 2007 to 2025). A benign or malignant brain and spinal cord tumor that arises from glial cells (astrocytes, oligodendrocytes, ependymal cells). "Research has indicated that among patients with low-grade glioma, ITGAV mRNA expression levels are linked to tumor immunity, immune checkpoints, immune checkpoint blockade, and response to chemotherapy." (PMID 37772261, 2023). "By analyzing publicly accessible scRNA-seq data from human gliomas via the SingleCell portal, we detected the predominant expression of ITGAV, ITGB3 and ITGB5 (encoding αv, β3 and β5 integrins, respectively) in clusters of myeloid cells, pericytes and endothelial cells." (PMID 40281508, 2025). "Similar to in SCLC, ITGAV expression showed significantly distinctive effects between cancers and non-cancers, particularly for cholangiocarcinoma, esophageal carcinoma, glioblastoma multiforme, glioma, acute myeloid leukemia, LGG, PAAD, and high-risk Wilms tumors (all AUCs > 0.9)." (PMID 35927660, 2022). "Univariate Cox regression analysis revealed that ITGAV expression was significantly associated with poor OS in several cancer types, including KIRP, lower-grade glioma (LGG), LIHC, mesothelioma (MESO), and pancreatic adenocarcinoma (PAAD)." (PMID 40775249, 2025). "We previously reported that ITGAV interactions with the ECM produced by differentiating GICs are associated with GIC growth signaling and glioma progression via the formation of a specific microenvironment, the so-called “differentiation niche”." (PMID 38309500, 2024). "The expression level of ITGAV in tumors and its effect in glioma cell lines were verified by experiments." (PMID 36388191, 2022). "Among the cell adhesion molecules, silencing TRAF3IP2 reduced ITGAV (Integrin-αV) expression which is known to be involved in the migration of glioma cells and is thus considered to contribute to invasiveness." (PMID 36046049, 2022). "At the same time, the expression of ITGAV mRNA was found to increase with increasing tumor invasiveness in gliomas of different grades (P < 0.05)." (PMID 36388191, 2022). "To further elucidate the role of ITGAV in immunity to lower grade gliomas, we also evaluated the differences in immune checkpoints between the two groups with high and low ITGAV expression levels." (PMID 36388191, 2022). "Here, the expression preference, prognostic value, and clinical traits of ITGAV were investigated using The Cancer Genome Atlas database (n = 528) and the Chinese Glioma Genome Atlas dataset (n = 458)." (PMID 36388191, 2022). "Elevated ITGAV expression was found in 19 cancers, such as glioblastoma multiforme, glioma, and brain lower grade glioma (LGG)." (PMID 35927660, 2022). "ITGAV, in both IHC and RNA-seq, is overexpressed in liver cancers, gliomas, head and neck cancers, and lung cancers." (PMID 30046394, 2018). "However, few reports of ITGAV have been detailed regarding gliomas, and the expression pattern and prognostic value of ITGAV are still unclear; thus, this subject is worthy of further study." (PMID 36388191, 2022). "In addition, the prognostic value of ITGAV mRNA expression in LGG was validated using the Chinese Glioma Genome Atlas (CGGA) dataset." (PMID 36388191, 2022). "Survival analysis based on the expression of individual integrin genes or a multigene signature revealed that high levels of ITGAV, ITGB3 and ITGB5 correlate with a poor prognosis in glioma patients." (PMID 40281508, 2025). "In MAN1C1-expressing glioma cells, the presence of highly glycosylated receptors, such as CD44 and integrins (ITGB1, ITGAV, ITGA8, ITGAB1) facilitates this interaction." (PMID 39333557, 2024). "To investigate the role of ITGAV in LGG, we evaluated the effect of ITGAV on lower–grade glioma cell proliferation." (PMID 36388191, 2022).
glioma (continued). "The quantitative real-time PCR method was used to evaluate mRNA expression of SEMA3(A-G), neuropilins (NRP1 and NRP2), plexins (PLXNA2 and PLXND1), cadherins (CDH1 and CDH2), integrins (ITGB1, ITGB3, ITGA5, and ITGAV), VEGFA and KDR genes in 59 II-IV grade glioma tissues." (PMID 33036421, 2020). "Taking two cell lines, e.g. DKMG (glioma) was predicted to be ITGAV-dependent; BL70 (Burkitt lymphoma) was predicted not to be ITGAV-dependent." (PMID 34042953, 2021).
ovarian carcinoma (15 papers, 2008 to 2024). A malignant neoplasm originating from the surface ovarian epithelium. "High expression of ITGAV in ovarian cancer tumor tissue from late stage tumors has been associated with poor prognosis." (PMID 35804849, 2022). "Increased expression of ITGAV in tumor tissue has been associated with poor prognosis in ovarian cancer." (PMID 33075095, 2020). "The expression levels of carboplatin resistance-associated proteins, AKR1B1, ITGAV, TGFβ1 and G6PD, in platinum resistant and relapsed human ovarian cancer samples are consistent with our observations in vitro data on control and carboplatin-resistant cells." (PMID 36463238, 2022). "Similar to what we observed in the early stage samples, CA125 and HE4 levels were elevated in the late stage ovarian cancer samples, while ITGAV and SEZ6L levels were higher in the healthy control samples." (PMID 35804849, 2022). "ITGAV and ABCA5 have been reported to be associated with ovarian cancer and ADIPOQ and PPARG are associated with polycystic ovary syndrome." (PMID 35052428, 2021). "The best characterised example of nuclear integrins is ITGAV/ITGB3 in ovarian cancer; in this case, nuclear localisation was cancer-specific, and induced proliferation without interfering with the adherence function of the plasma-membrane located fraction." (PMID 34253873, 2021). "However, both tissue and serum levels of ITGAV have been shown to be present at reduced levels in ovarian cancer compared to benign tumors and borderline ovarian cancers." (PMID 35804849, 2022). "It is necessary to investigate whether ITGAV could regulate the activation of latent TGFβ1 in 3D-cultured ovarian cancer spheroids and whether ITGAV is involved in the ITGB6-regulated activation of latent TGFβ1 in 3D-cultured ovarian cancer spheroids." (PMID 34621667, 2021). "This supports the hypothesis that Wnt5A modulates cell proliferation and migration of ovarian cancer cells through up-regulation of ITGAV expression." (PMID 33723319, 2021). "First, we silenced the expression of ITGAV in 3D-cultured ovarian cancer spheroids using siRNA." (PMID 34621667, 2021). "In epithelial ovarian cancer cells, ITGAV expression is essential for peritoneal dissemination." (PMID 33075095, 2020). "In addition, ITGAV expression has been correlated with increased expression of the matrix metalloprotease MMP9 in ovarian cancer effusions, which could impact ITGAV shedding into the serum in late stage ovarian cancer." (PMID 35804849, 2022). "However, ITGAV might be play a role in the ITGB6-regulated activation of latent TGFβ1 in 3D-cultured ovarian cancer spheroids." (PMID 34621667, 2021). "We found that anti-ITGB6 antibody was more effective in inhibiting the phosphorylation level of Smad3 in 3D-cultured NC-ITGAV cells than in 3D-cultured si-ITGAV cells, implying that ITGAV might play a role in ITGB6-regulated activation of latent TGFβ1 in 3D-cultured ovarian cancer spheroids." (PMID 34621667, 2021). "In ovarian cancer, FOXM1 also induces the expression of integrins and matrix proteins: ITGB1, ITGAV, ITGA5, LMNB1, and FN1, which may facilitate adhesion of ovarian cancer cells to new organs." (PMID 34205406, 2021). "In addition, as the binding partner of ITGB6, ITGAV, had no independent effect on activating latent TGFβ1 in 3D-cultured ovarian cancer spheroids." (PMID 34621667, 2021). "However, no prognostic role of AKRIBI, ITGAV and G6PD was evident in TCGA data and GSE (from Gene Expression Omnibus) datasets which included 738 high grade ovarian cancer patients that had undergone chemotherapy treatments." (PMID 36463238, 2022). "Interestingly, ITGAV and SEZ6L have not previously been identified as early stage ovarian cancer biomarkers, and the levels of both proteins were significantly decreased in sera from women with early stage ovarian cancer compared to healthy controls." (PMID 35804849, 2022).
glioblastoma (14 papers, 2013 to 2025). The most malignant astrocytic tumor (WHO grade IV). "Our findings demonstrate that the mitochondria-derived peptide, humanin, plays a significant role in enhancing glioblastoma progression through the intratumoral activation of the integrin alpha V (ITGAV)-TGF beta (TGFβ) signaling axis." (PMID 38942749, 2024). "Similarly, integrins CD49a (ITGA1), CD49d (ITGA4), CD51 (ITGAV), and CD11a (ITGAL) were selected for further validation based on elevated gene expression in glioblastoma-infiltrating T cells." (PMID 35464424, 2022). "Further analysis revealed that macrophages expressing high levels of NT5E are characterized by elevated expression of chemokines and chemokine receptors such as CCR5, CCR2, ITGAV/ITGB5, and CSF1R, which may play a role in the recruitment of macrophages into the glioblastoma microenvironment." (PMID 40191733, 2025). "Despite high proportions of T cells positive for ITGAV, we did not detect CD51 protein in any T-cell subsets in glioblastoma biopsies or paired blood samples." (PMID 35464424, 2022).
pancreatic cancer (14 papers, 2018 to 2026). "The role of ITGAV in promoting cancer progression has been experimentally confirmed in hepatocellular carcinoma and pancreatic cancer." (PMID 40423332, 2025). "For illustration, ITGAV overexpression stimulated the synergistic effect of integrin and selectin, which promoted adhesion between pancreas cancer cells and peritoneal mesothelial cells, ultimately resulting in the development of PAAD." (PMID 39690926, 2024). "Although ITGAV expression is almost undetectable under physiological conditions, its increased expression has been observed in lung and pancreatic cancers." (PMID 39075581, 2024). "Analysis using the Xiantao online tools revealed that the CD274 (PD-L1) gene exhibits high expression levels in tumor samples from hepatocellular carcinoma, pancreatic cancer, renal cancer, and urothelial cancer, alongside elevated expression of αv (ITGAV) and β3 (ITGB3) genes." (PMID 41601637, 2026). "Finally, the role of ITGAV in regulating cancer progression was experimentally verified using hepatocellular carcinoma and pancreatic cancer as examples." (PMID 40018050, 2025). "KH‐type splicing regulatory protein (KHSRP) binds to and stabilizes m6A of the met proto‐oncogene, receptor tyrosine kinase (MET), integrin subunit alpha v (ITGAV), and integrin subunit beta 1 (ITGB1) mRNAs, activating the FAK signaling pathway and promoting pancreatic cancer growth." (PMID 40448344, 2025). "For example, upregulated ITGAV stimulated the synergistic effect of integrin and selectin, which promoted adhesion between PAAD and peritoneal mesothelial cells, finally leading to the growth of pancreatic cancer." (PMID 35927660, 2022).
gastric cancer (13 papers, 2016 to 2025). A primary or metastatic malignant neoplasm involving the stomach. "We also found overexpression of integrin family members including ITGB1 and ITGAV, which is associated with poor overall survival of gastric cancer patients." (PMID 36520032, 2023). "Both ITGB1 and ITGAV play important roles promoting the invasion and migration of gastric cancer cells in vitro and are associated with poor prognostic outcomes." (PMID 36520032, 2023). "In addition, significantly high expression of ITGAV had also been observed in highly prevalent digestive system cancers such as gastric cancer." (PMID 40018050, 2025). "Emerging pieces of evidence indicate that the ITGAV gene leads to the development and progression of various malignancies, such as colon carcinoma, pancreatic adenocarcinoma, esophageal adenocarcinoma, gastric cancer, hepatocellular carcinoma." (PMID 39690926, 2024). "Moreover, the significant association of ITGAV expression and immune infiltrating cells (e.g., CD8+T cell and neutrophil) in certain cancers (e.g., colon cancer and gastric cancer) has been reported before, implying its potential in immunotherapy." (PMID 35927660, 2022). "A number of proteins have been reported to play important roles in gastric cancer metastasis, such as ITGB1, ITGAV, and LAMA4." (PMID 36520032, 2023).
lung carcinoma (13 papers, 2018 to 2025). "Through disease ontology, ITGAV-PRLEGs are involved in some diseases, including SCLC and non-small-cell lung carcinoma, suggesting associations between ITGAV and lung cancers." (PMID 35927660, 2022). "In conclusion, our results revealed that a potential isoform of IL-32, IL-32γ inhibits CSC self-renewal and stem cell niche, which is relevant to the growth of tumors and the recurrence of lung cancer through downregulation of the ITGAV-mediated STAT5 pathway." (PMID 31263095, 2019). "Furthermore, IL-32γ overexpression can promote the growth and apoptosis of lung cancer stem cells, but this promotive effect can be reversed by ITGAV, indicating that the STAT5 pathway mediated by ITGAV can promote the growth of lung cancer stem cells." (PMID 39239559, 2024). "In our data, the expression of ITGAV was increased in lung cancer patient tissues." (PMID 31263095, 2019). "In addition, the lack of IGF1R or ITGAV renders epithelial cancer cells insensitive to TGFβ-mediated EMT induction, as demonstrated in lung cancer cells following IGF1R inhibition." (PMID 39075581, 2024).
hepatocellular carcinoma (12 papers, 2020 to 2026). A malignant tumor that arises from hepatocytes. "Recent studies have shown that ITGAV is highly expressed in osteosarcoma, hepatocellular carcinoma, and oesophageal adenocarcinoma tissues compared to normal tissues." (PMID 34709754, 2021). "For example, in hepatocellular carcinoma, lncRNA-AY could promote hepatocellular carcinoma metastasis via induction of chromatin modification for ITGAV transcription." (PMID 34289835, 2021).